JAG1 (jagged canonical Notch ligand 1)
Diseases named in the same sentence as JAG1 in open-access papers (continued):
Sharing a sentence is not in itself a finding about the gene and the disease.
ovarian carcinoma (continued). "In ovarian cancer, DAC upregulated miR-199, which suppressed tumor growth and enhanced cytotoxicity of cisplatin in vitro and in vivo by shutting down JAG1 mRNA and its overexpression, thus suggesting the targeting of chromatin remodelers to indirectly modulate Notch signaling with miRNAs." (PMID 34680255, 2021). "JAG1 contains a highly conserved miR-199b-5p binding site at nucleotides 135—141 in its 3'UTR and is a trans-membrane protein acting as a key ligand of Notch receptors in ovarian cancer." (PMID 24659709, 2014). "Antibodies against the Notch ligand DLL4 have been tested clinically against tumor angiogenesis, but are unlikely to block Notch3 signaling, which appears to be activated by the ligand JAG1 in ovarian cancers where Notch3 signaling has not become ligand-independent." (PMID 32525899, 2020). "Blocking the JAG1-Notch1 signaling axis by either re-expression of miR-199b-5p, siRNA-mediated JAG1 knockdown or treatment with the Notch-specific inhibitor γ-secretase (GSI) dramatically abrogated tumor growth and enhance cisplatin-induced cytotoxicity in vitro and in vivo in ovarian cancer cells." (PMID 24659709, 2014).
colorectal cancer (47 papers, 2010 to 2026). A primary or metastatic malignant neoplasm that affects the colon or rectum. "We identified one tagging SNP (rs6040062) in JAG1, which was associated with shorter OS of colorectal cancer patients." (PMID 32751332, 2020). "Genes of Notch signaling pathway such as Notch1, Notch2, HES1, DLL1, and JAG1 have been reported to be associated with the pathological tumor characteristics and degree of differentiation in colorectal cancer." (PMID 29100272, 2017). "Consistently, silencing of Jagged1 in OXA- or 5-FU–resistant colorectal cancer subpopulations restores their sensitivity to chemotherapy, confirming that drug response is Jag1-ICD–dependent." (PMID 41294868, 2025). "Circ‐NSD2 upregulates JAG1 in colorectal cancer, while circ_0006476 modulates DLL4 in atherosclerosis, illustrating how circRNAs regulate Notch ligands to amplify pathway activity across diseases." (PMID 40761890, 2025). "In fact, Notch signaling exhibits context‐dependent roles, with circFBXW7 suppressing NOTCH 1 in T‐ALL (tumor suppressor) versus circ‐NSD2 activating JAG1/NOTCH 1 in colorectal cancer (oncogene)." (PMID 40761890, 2025). "JAG1 has been reported as a target molecule of β‐catenin in colorectal cancer, and JAG1 was shown to induce NOTCH3 expression in endometrial epithelial cells." (PMID 37272232, 2023). "FTX was proven to promote the malignant progression of colorectal cancer by targeting the miR-214-5p-JAG1 axis or directly binding to miR-192-5p." (PMID 37106382, 2023). "NSD2 circular RNA aggravates liver metastasis of colorectal cancer by regulating miR-199b-5p/DDR1/JAG1 axis." (PMID 37709489, 2023). "There is now compelling evidence that overexpression of JAG1 can promote metastasis of colorectal carcinoma by inducing epithelial-mesenchymal transition." (PMID 36071128, 2022). "Aberrant NOTCH signaling promotes the development and progression of colorectal cancer and is partly driven by the overexpression of JAG1, a ligand of NOTCH4." (PMID 32751332, 2020). "Eleven tagging SNPs in four genes (EFNB2, MMP2, JAG1 and KDR) were significantly associated with overall survival of colorectal cancer patients." (PMID 32751332, 2020). "Jag2 was the most frequently observed ligand that was overexpressed in 52%, while a higher expression of Jag1, Dll1, Dll3, and Dll4 was found in 26%, 25%, 25%, and 39% colorectal cancers, respectively." (PMID 32211044, 2020). "JAG1 has been considered as an attractive target for colorectal cancer therapy, as it seems to be a more specific target than other members of the NOTCH pathway." (PMID 32751332, 2020). "Our data provide an explanation to Jag1 dependence in cancer, and reveal that Jag1–Notch1 interference provides therapeutic benefit in a subset of colorectal cancer and FAP syndrome patients." (PMID 30065304, 2018). "Similarly, overexpression of JAG1 in colorectal cancer has been reported to induce EMT and promote metastasis." (PMID 37414855, 2023). "Several investigations indicate that overexpression of Notch1, Jag1, and Jag2 was found in human intestinal adenomas, implying that elevated Notch signaling might be responsible for colorectal cancer initiation." (PMID 32211044, 2020). "High expression of the ligand JAG1, which is regulated by β-catenin, may upregulate the expression of Notch-1 in colorectal cancer, which persists throughout the process of tumor growth." (PMID 31198409, 2019). "Similarly, JMJD2C knockdown impaired sphere-forming ability through decreased β-catenin recruitment to the JAG1 gene promoter in colorectal cancer cells." (PMID 29700375, 2018). "One intronic variant in JAG1 (rs6040062) was significantly associated with shorter overall survival (HRG > C: 1.36, 95% CI: 1.15–1.61, p-value: 0.0003) and recurrence-free survival (HRG > C: 1.31, 95% CI: 1.09–1.57, p-value: 0.004) of colorectal cancer patients." (PMID 32751332, 2020).
colorectal cancer (continued). "In this regard, the soluble Jag1-ECD, derived from endothelial cells (ECs), has been shown to promote colorectal cancer progression in a paracrine manner." (PMID 41294868, 2025). "The effect of JAG1 and NOTCH1 on pluripotency in colorectal cancer cells was observed in vitro where constitutive activation of Notch in colon tumor cell lines resulted in increased expression of EMT and stemness associated proteins." (PMID 37860822, 2023). "It has been demonstrated that FTX is distributed in the colorectal cancer (CRC) cell nucleus and cytoplasm and drives the malignant progression of CRC by regulating miR-214-5p/JAG1 axis." (PMID 37993428, 2023). "GATA-binding protein 1 (GATA1) participates in tumor progression by activating JAG1/Notch and PI3K/AKT pathways in ovarian and colorectal cancer, respectively." (PMID 38254939, 2023). "In addition to JAG1 and DLL4, the JAG2/NOTCH pathway also exerts a cancer-promoting effect in colorectal cancer cells, as JAG2 knockdown in colorectal cancer cells inhibits their expression of CD133, decreasing in a similar manner their ability to form spheroids and to induce metastasis." (PMID 37860822, 2023). "In 239 human colorectal cancer patient samples, MFNG imposes a negative correlation between Jag1 and Notch, being high Jag1 in the absence of MFNG predictive of poor prognosis." (PMID 30065304, 2018).
glioma (44 papers, 2010 to 2026). A benign or malignant brain and spinal cord tumor that arises from glial cells (astrocytes, oligodendrocytes, ependymal cells). "A study demonstrated that Yes-associated protein 1 (YAP1) promotes the metastasis of U251 glioma cells by upregulating Jagged-1 (JAG1) expression and activating the Notch signal pathway." (PMID 38474320, 2024). "In our previous study, JAG1 was highly expressed in human glioma patients, and some tumor cells exhibited nuclear JAG1 expression." (PMID 38092725, 2023). "Another interesting protein in the NOTCH pathway is Jagged1 (JAG1) that is able to promote glioma-initiating cells (GICs) in HGG." (PMID 37887005, 2023). "We downregulated JAG1 in low-grade gliomas to assess its influence on the proliferation and migration of these tumors." (PMID 38022677, 2023). "Moving forward, it remains to be studied in other types of human cancers, given that the JICD1-TWIST1-MMP2 and MMP9 axes correlate with GBM aggressiveness, and nuclear-localizing JAG1 is observed in glioma patients." (PMID 38092725, 2023). "JAG1 regulates cell signaling and induces oncogenic phenotypes, such as stemness in glioma, via JICD1 formation." (PMID 38092725, 2023). "Various studies have demonstrated increased expression of distinct components of Notch signaling pathway (such as Notch1, Notch2, Dll1, Dll4 and Jag1) and Notch target genes (Hey1, Hey2, Hes1) in glioma cell lines or primary human glioma samples including GBM." (PMID 36010607, 2022). "To conclude, lncRNA HOXA-AS2 facilitates KDM2A/JAG1 expression to promote Treg cell proliferation and immune tolerance in glioma by binding to miR-302a." (PMID 35181676, 2022). "In summary, our investigation revealed that lncRNA HOXA-AS2 upregulated KDM2A expression and promoted JAG1 expression in glioma cells by competitively binding to miR-302a." (PMID 35181676, 2022). "To investigate the role of the lncRNA HOXA-AS2/miR-302a/KDM2A/JAG1 axis in glioma progression, we established a xenograft mouse model, in conjunction with lncRNA HOXA-AS2 silencing and JAG1 overexpression." (PMID 35181676, 2022). "Taken together, our study demonstrated that lncRNA HOXA-AS2 promoted glioma progression in vivo by mediating the miR-302a/KDM2A/JAG1 axis." (PMID 35181676, 2022). "Linc-OIP5 overexpression enhances glioma tumorigenesis through Notch activation, upregulating JAG1, Notch-1 and Hes1 expressions." (PMID 36229883, 2022). "PlncRNA-1 overexpression induces glioma progression through boosting expressions of Notch1, JAG1 and Hes1, stimulating Notch signal." (PMID 36229883, 2022). "RT-qPCR and IHC results presented that JAG1 mRNA and protein expression was high in glioma tissues and shared a positive correlation with KDM2A expression in glioma tissues." (PMID 35181676, 2022). "We also verified the correlation of miR-512-5p and JAG1 expression in glioma tissues (n = 71) and NBTs (n = 8) by RT-qPCR and western blotting." (PMID 33795521, 2021). "The upregulation of Notch ligand JAG1 and targets Hey1, Hey2, Hes1 in brain tissues of glioma patients compared to that of healthy brain tissues also highlight the Notch signaling pathway as a potential therapeutic target in glioma patients." (PMID 33381038, 2020). "Down-regulation of Notch1, Dll1, or Jag1 by RNA interference induces apoptosis and inhibits proliferation in multiple glioma cell lines." (PMID 28950865, 2017). "To date, it has been shown that Notch1 and its ligands, Dll1 and Jag1, are overexpressed in many glioma cell lines and primary human gliomas." (PMID 28950865, 2017). "It has been shown that Notch1 and its ligands, Dll1 and Jag1, are overexpressed in many glioma cell lines and primary human gliomas." (PMID 28950865, 2017). "Although our model provides a new theoretical framework to investigate the effects of Dll1, Jag1 and Fringe in the Notch1 signaling system in glioma cells, it ignores the spatial effects which can be also important." (PMID 28950865, 2017).
glioma (continued). "A recent study demonstrated that an oncogenic transcription factor Lim domain only 2 (LMO2) increases glioma stem cells by inducing JAG1 expression." (PMID 27029061, 2016). "For example, JAG1 expressed by both tumor and endothelial cells plays an important role in glioma/glioblastoma-initiating cells." (PMID 25309874, 2014). "The upregulation of KDM2A contributed to regulatory T-cell proliferation and immune tolerance in glioma samples and a tumor xenograft mouse model as it demethylated the jagged 1 (JAG1) promoter region, elevating JAG1 expression and contributing to regulatory T-cell proliferation." (PMID 39765675, 2024). "Several studies demonstrated that JAG1 staining was strongly expressed only in glioma tissue." (PMID 37887005, 2023). "JAG1 upregulation was found in GBM, and JAG1 silencing inhibited glioma cell proliferation." (PMID 33795521, 2021). "Western blotting assays showed that JAG1 positively correlated with glioma metastasis." (PMID 33795521, 2021). "Furthermore, the Spearman correlation test indicated that JAG1 expression was negatively correlated with miR-512-5p expression in glioma tissues (r = -0.3352 and p = 0.043, respectively)." (PMID 33795521, 2021). "The purpose of this paper is to present a computational model for Notch1 signaling pathway in glioma cell lines and primary human gliomas based on intertwined dynamics with cis-inhibition and trans-activation involving the proteins Notch1, Dll1, Jag1, and Lunatic Fringe." (PMID 28950865, 2017). "Besides Fringe, Dll1 and Jag1 also play critical roles in glioma cell fate decisions due to combinatorial effects between them." (PMID 28950865, 2017). "Interestingly, JAG1 can prevent both spontaneous apoptosis, for example, in glioma and prostate cancer cells, as well as chemotherapy-induced cell death." (PMID 25309874, 2014). "Interestingly, a previous immunohistochemical assay showed an increase in JAG1 expression with higher WHO grades of gliomas (levels from II to IV), which indicates JAG1 protein expression maybe associated with progression of the disease." (PMID 38022677, 2023). "Moreover, the upregulation of JAG1 can promote the malignant progression of glioma." (PMID 33795521, 2021). "Tenascin-C can activate the Notch pathway to promote glioma proliferation by increasing ADAMTS15 and Jagged1 (JAG1) expression." (PMID 37325048, 2023). "The expression of both JAG1 and ANXA2 was higher in patients with high-grade glioma than in patients with grade II and III glioma and were positively correlated with each other." (PMID 37834227, 2023). "We found aberrant upregulation of lncRNA HOXA-AS2, lysine demethylase 2A (KDM2A), and jagged 1 (JAG1) and a downregulation of microRNA-302a (miR-302a) in glioma specimens." (PMID 35181676, 2022). "Two key ligands mediate Notch paracrine receptors in glioma stem cells (GSCs), DLL4, and JAG1, expressed in epithelial cells (ECs)." (PMID 36643842, 2021). "Our analysis indicated that JAG1, PVT1, H19, and HAR1A were aberrantly expressed in IDH mutant gliomas and were core lncRNA genes in regulating the expression of protein-encoding gene in IDH mutant gliomas." (PMID 33329315, 2020). "To address if the NOTCH pathway was active in our glioma cell lines, we analyzed the gene expression profile of NOTCH receptors (NOTCH1-4), ligands (DLL 1,3,4 JAG 1,2) and target (HES1, HEY1,2) genes." (PMID 27183910, 2016). "There is some precedence for a positive regulatory loop in which Notch regulates the expression of ligands, including Jag1 in NIH 3T3 cells and Dll1 in glioma cells." (PMID 21352545, 2011). "In contrast, neither JAG1-TWIST1-MMP2 nor JAG1-TWIST1-MMP9 axis was correlated with the prognosis of IDH-mutant glioma patients." (PMID 38092725, 2023). "The Notch /JAG1 signaling pathway can work directly with other essential pathways such as MMP9 and VEGF to regulate glioma growth and malignancy, which defines patients’ physical condition with glioma." (PMID 36643842, 2021).
glioma (continued). "Additionally, more research could be conducted to confirm the downstream genetic targets of the KDM2A/TGF-β/Smad pathway and the KDM2A/JAG1 axis in GBM and glioma to improve treatments and mitigate their secondary effects in patients." (PMID 39765675, 2024).
prostate carcinoma (41 papers, 2010 to 2026). A carcinoma that arises from epithelial cells of the prostate gland. "Increased JAG1 showed a significant, but modest association with worse prostate cancer progression-free survival in the TCGA PanCancer Atlas prostate adenocarcinoma cohort." (PMID 36229464, 2022). "JAG1 expression is upregulated in high-grade metastatic prostate carcinomas and associated with poor disease-free survival of patients with prostate cancer." (PMID 36428807, 2022). "Genetic manipulation of endothelial Jagged1 in a mouse model of prostate cancer revealed that loss of endothelial Jag1 had an inhibitory effect in the neo-angiogenic and maturation responses." (PMID 33198378, 2020). "After characterizing the neo-vasculature of two different tumor models in endothelial Jag1 specific mutants, we aimed to understand how the different vascular phenotypes were able to cause such significant differences in progression of prostatic cancer in mice." (PMID 26213336, 2015). "In prostate cancer, Jag1-ICD has been shown to upregulate the expression of androgen receptor variants (AR-Vs) and to enhance AR transactivation under both androgen-dependent and -independent conditions." (PMID 41294868, 2025). "They detected that miRNA-34a mimic attenuated the paclitaxel-chemoresistance of PC-3PR prostate cancer cells through direct suppression of JAG1 and Notch1expressions." (PMID 38057687, 2024). "Intriguingly, all JAG1-positive prostate carcinomas express JICD although JICD function in prostate cancer (PC) cells is poorly understood." (PMID 36428807, 2022). "On a separate note, Notch signaling ligand—Jag1—has been independently reported to be a marker of poor prostate cancer progression." (PMID 27749937, 2016). "In support of this, JAG1, a member of the TNFα signaling via NFĸB hallmark, was enriched in ICC/IDC compared to lower Gleason patterns, other Gleason pattern 4 histological subtypes of prostate cancer, and benign prostate luminal epithelial cells." (PMID 36229464, 2022). "All JAG1-positive prostate carcinoma tissues express cytoplasmic JICD although JICD function in PC cells is largely unknown." (PMID 36428807, 2022). "In this study, we found that the overexpression of the processed intracellular domain of JAG1 (JICD) increased the expression of AR-Vs in prostate cancer (PC) cells and enhanced the transactivation of ARs in an androgen-independent as well as androgen-dependent manner." (PMID 36428807, 2022). "Besides, the discovery of DANCR/miR-34a-5p/JAG1 axis provides a novel perspective on the treatment of prostate cancer." (PMID 33292218, 2020). "Similarly, previous studies have demonstrated that down-regulation of Jag1 induces cell growth inhibition and S phase cell cycle arrest in prostate cancer cells." (PMID 26213336, 2015). "In addition, JAG1, one of the ligands for the Notch receptor, is proposed as a prostate cancer marker." (PMID 20500816, 2010). "In addition, expression of JAG1 protein is increased in metastatic prostate cancer and prostate cancer cells suggesting Notch1 and JAG1 mediated signaling may enhance carcinogenesis." (PMID 20070897, 2010). "We observed that endothelial Jag1 over-expression accelerated the growing rate of LLC subcutaneous tumor transplants and contributed to the progression and development of prostate cancer in TRAMP mice." (PMID 26213336, 2015). "The TRAMP endothelial specific Jag1 mutants, TRAMP.eJag1OE and TRAMP.eJag1cKO, were sacrificed at 18 and 24 weeks of age, for early and late stages of prostate cancer development, and the prostates collected for analysis." (PMID 26213336, 2015). "Indeed, in silico analysis of a previously published dataset of human prostate cancer specimens confirms that both NOTCH1 and JAG1 are upregulated at the tumor stage." (PMID 29259971, 2017).
prostate carcinoma (continued). "In addition, the overexpression of JAG1 and JICD in PPC-1 cells (AR-negative PC-3-derived prostate cancer cells) markedly enhanced the androgen-dependent and androgen-independent transactivation of exogenous AR-FL, AR-NTD-DBD, and AR-V7 in a dose-dependent manner." (PMID 36428807, 2022). "Transcriptional analysis revealed that ALK1Fc systemically blocks the induction of JAG1 mRNA in the presence of BMP9 supporting our hypothesis that the crosstalk between BMP9 and NOTCH signaling may have clinical implications in prostate cancer." (PMID 29259971, 2017). "RNAscope of RP tissue from ICC1-7 and from an extended independent validation cohort confirmed higher JAG1 expression in ICC/IDC compared to benign luminal epithelial cells, Gleason pattern 3, and Gleason pattern 4 non-ICC (NC) prostate cancer." (PMID 36229464, 2022).